MRGBP (MRG domain binding protein)
Description:
Component of the NuA4 histone acetyltransferase (HAT) complex which is involved in transcriptional activation of select genes principally by acetylation of nucleosomal histones H4 and H2A. This modification may both alter nucleosome - DNA interactions and promote interaction of the modified histones with other proteins which positively regulate transcription. This complex may be required for the activation of transcriptional programs associated with oncogene and proto-oncogene mediated growth induction, tumor suppressor mediated growth arrest and replicative senescence, apoptosis, and DNA repair. NuA4 may also play a direct role in DNA repair when recruited to sites of DNA damage.
Synonyms: Urcc4; C20orf20; FLJ10914; MRG15BP; Eaf7
Tractability: PROTAC: UniProt records ubiquitination sites on it; ubiquitination databases record sites on it; its protein half-life has been measured.
Gene: Protein-coding gene on chromosome 20 (62,796,473 to 62,801,729, forward strand). Ensembl gene ENSG00000101189.
Subcellular location: Nucleus
Subcellular location (Human Protein Atlas): Nucleoplasm
Pathways (Reactome):
Chromatin organization: HATs acetylate histones
Gene Ontology:
Molecular function: protein binding
Biological process: positive regulation of double-strand break repair via homologous recombination; regulation of cell cycle; positive regulation of DNA-templated transcription; regulation of apoptotic process; regulation of double-strand break repair; regulation of transcription by RNA polymerase II; regulation of DNA-templated transcription
Cellular component: NuA4 histone acetyltransferase complex; nucleoplasm; nucleosome; H4/H2A histone acetyltransferase complex; nucleus
Genetic constraint (gnomAD): Loss-of-function variants: 5 observed, 18.32 expected, observed/expected ratio (o/e) 0.27, 90% interval 0.14 to 0.57. The upper end of that interval is the gene's LOEUF score, 0.57, which puts it in group 2 of 6, group 1 being the genes least tolerant of losing a copy. Missense variants: 227 observed, 250.27 expected, observed/expected ratio (o/e) 0.91, 90% interval 0.81 to 1.01. Synonymous variants: 118 observed, 96.71 expected, observed/expected ratio (o/e) 1.22, 90% interval 1.05 to 1.42.
Homologues: Orthologues: chimpanzee MRGBP (100% identical), macaque MRGBP (99% identical), guinea pig MRGBP (98% identical), mouse Mrgbp (97% identical), dog MRGBP (96% identical), pig MRGBP (96% identical), tropical clawed frog mrgbp (66% identical), zebrafish mrgbp (65% identical), rat Mrgbp (59% identical), Drosophila melanogaster MrgBP (33% identical).
Diseases named in the same sentence as MRGBP in open-access papers:
MRGBP is named in the same sentence as 29 diseases in open-access papers, as found by Europe PMC text mining. Sharing a sentence is not in itself a finding about the gene and the disease. The quoted sentences say what the papers report.
pancreatic cancer (6 papers, 2017 to 2023). "Similarly, in pancreatic cancer, elevated expression of MRGBP was previously reported as positively associated with poor prognosis." (PMID 34660575, 2021). "The re-expression of another downregulated miRNA, miR-137 significantly blocked the migration and invasion of pancreatic cancer cells by down-regulating MRG domain binding protein (MRGBP), which has been documented to be upregulated in malignant tumors." (PMID 38139352, 2023). "Overexpression of MRG domain binding protein (MRGBP) has been documented in malignant tumors, including pancreatic cancer." (PMID 34680441, 2021). "So far, little has been known about the expression pattern and cellular functions of MRGBP in pancreatic cancer." (PMID 28969065, 2017). "Further studies indicated that MRGBP might play an epigenetic regulatory role as a direct downstream target gene of miR-137 in pancreatic cancer." (PMID 35924262, 2022). "Therefore, the loss of miR-137 may act as a new tumor promoter, facilitating overexpression of MRGBP in pancreatic cancer." (PMID 34680441, 2021). "In this study, we observed that MRGBP expression was commonly upregulated in PDAC tissues comparing with adjacent noncancerous pancreatic tissues and normal pancreas, and was strongly associated with survival in pancreatic cancer from two independent GEO datasets." (PMID 28969065, 2017).
colorectal cancer (5 papers, 2010 to 2022). A primary or metastatic malignant neoplasm that affects the colon or rectum. "In summary, the expression of MRGBP is enhanced in the majority of colorectal cancers, and its expression is associated with the growth of cancer cells." (PMID 20051959, 2010). "We have shown for the first time that MRGBP (C20orf20) is up-regulated in the majority of colorectal cancer, and that its elevated expression is implicated in the proliferation of cancer cells." (PMID 20051959, 2010). "MRGBP was positively associated with inflammation (cor = 0.329, P = 0.012) and quiescence (cor = 0.323, P = 0.013), while negatively correlated with DNA repair (cor = −0.406, P = 0.002) in colorectal cancer." (PMID 34660575, 2021). "Similarly, previous studies have found that MRGBP was associated with DNA replication, microchromosome maintenance, and cell division in colorectal cancer." (PMID 34660575, 2021). "Previous reports have shown that expression of MRGBP was upregulated in colorectal carcinoma and might be associated with the transformation from adenoma to carcinoma in colorectal carcinogenesis." (PMID 28969065, 2017). "MRGBP promotes colorectal cancer by playing advantage in cell proliferation or cancer cell division." (PMID 35924262, 2022). "MRGBP expression is upregulated in colorectal cancer, and MRGBP plays an essential role in cancer cell proliferation by regulating BRD8." (PMID 35924262, 2022). "The role of MRGBP in PDAC cell proliferation is in agreement with the previous reports in colorectal cancer and cutaneous squamous cell carcinoma." (PMID 28969065, 2017). "The elevated expression of MRGBP was observed in colorectal cancer tissues by quantitative PCR as well as immunohistochemical analyses." (PMID 20051959, 2010). "In this report, we show, for the first time, that MRGBP expression was frequently elevated in colorectal cancer, and that it has an important function in the growth of cancer cells." (PMID 20051959, 2010). "However, in most colorectal cancers, MRGBP expression is increased and it promotes colorectal carcinogenesis by providing an advantage in cell proliferation and cancer cell division." (PMID 34660575, 2021). "It has been demonstrated that MRGBP was upregulated in multiple types of cancer such as colorectal cancer, cervical cancer, prostate cancer, and cutaneous squamous cell carcinoma, and has been proved to increase replication, induce apoptosis, reduce growth and promote invasiveness." (PMID 28969065, 2017). "Notably, suppressed MRGBP expression by MRGBP short hairpin RNA inhibited proliferation of colorectal cancer cells." (PMID 20051959, 2010). "This revealed MRGBP played an important role in the progression of adenoma to cancer and it might have potential clinical applications as a highly specific biomarker for colorectal cancer." (PMID 34660575, 2021). "Similarly, elevated MRGBP expression was observed in colorectal cancer cell lines." (PMID 34660575, 2021). "Our results strongly suggested that MRGBP promote PDAC progression, which is similar to the previous studies in other types of cancer, such as prostate cancer, colorectal cancer, cervical cancer and squamous cell carcinoma." (PMID 28969065, 2017). "As RNA interference against BRD8 also suppressed proliferation of colorectal cancer cells, BRD8 may be an important down-stream target of MRGBP." (PMID 20051959, 2010).
adenoma (3 papers, 2012 to 2021). A neoplasm arising from the epithelium. "Also, analysis of altered genes in 37 colorectal adenomas and 31 adenocarcinomas showed that MRGBP expression was significantly higher in carcinomas compared to adenomas." (PMID 34660575, 2021).
cutaneous squamous cell carcinoma (3 papers, 2017 to 2021). "MRGBP is upregulated in several types of cancers such as colorectal, cervical, prostate, pancreatic, and cutaneous squamous cell carcinomas and has been proved to increase replication, induce apoptosis, reduce growth and promote aggressiveness." (PMID 34660575, 2021). "Another tumor, cutaneous squamous cell carcinoma, in which MRGBP is thought to be overexpressed." (PMID 34660575, 2021).
pancreatic ductal adenocarcinoma (3 papers, 2017 to 2022). An infiltrating adenocarcinoma that arises from the epithelial cells of the pancreas. "However, the expression pattern and underlying mechanism of MRGBP in pancreatic ductal adenocarcinoma (PDAC) remain unknown." (PMID 28969065, 2017). "MRGBP is frequently upregulated in pancreatic ductal adenocarcinoma tissues and cell lines, and the upregulation of MRGBP is positively correlated with TNM stage and poor prognosis." (PMID 35924262, 2022).
prostate carcinoma (3 papers, 2017 to 2022). A carcinoma that arises from epithelial cells of the prostate gland. "MRGBP was found to be expressed in human prostate cancer model cells and promote replication and invasion of these cells." (PMID 35924262, 2022). "Another study showed that MRGBP expression was higher in most prostate cancer cell lines than in normal prostate cell lines and was able to enhance their aggressiveness." (PMID 34660575, 2021). "It has also been shown that MRGBP accelerates androgen receptor-mediated transactivation and promotes the growth of androgen receptor-positive prostate cancer cells." (PMID 34660575, 2021).
colorectal tumours (2 papers, 2010 to 2022). "MRG-binding protein (MRGBP) or C20orf20, encoding a subunit of TRRAP/TIP60-containing histone acetyltransferase complex, was up-regulated in the majority of colorectal tumours." (PMID 20051959, 2010). "Studies have shown that MRG-binding protein (MRGBP) is upregulated in most colorectal tumours." (PMID 35924262, 2022).
hepatocellular carcinoma (2 papers, 2021 to 2022). A malignant tumor that arises from hepatocytes. "The results showed that MRGBP expression was higher in adrenal cortical carcinoma, urothelial bladder carcinoma, hepatocellular carcinoma, oesophagal carcinoma, and head and neck squamous cell carcinoma than in adjacent normal tissues." (PMID 35924262, 2022). "This study investigated the expression change, prognostic values, and potential regulatory mechanisms of mortality factor on chromosome 4 (MORF4)-related gene-binding protein (MRGBP) in hepatocellular carcinoma (HCC)." (PMID 33761715, 2021).
lung carcinoma (2 papers, 2021 to 2022). "Furthermore, mutations in DNase I hypersensitive sites (DHS) may alter lung cancer susceptibility by regulating the expression of surrounding genes, a process closely related to MRGBP." (PMID 35924262, 2022). "MRGBP expression in colorectal, prostate, and lung cancers is consistent with their previous studies and it was also confirmed by our immunohistochemical results in LGG." (PMID 34660575, 2021).
acute lymphoblastic leukemia (1 paper, 2021). Leukemia with an acute onset, characterized by the presence of lymphoblasts in the bone marrow and the peripheral blood. "We found that MRGBP was positively associated with DNA repair (cor = 0.479, P = 0.007), while negatively correlated with angiogenesis (cor = −0.363, P = 0.049) in acute lymphoblastic leukemia." (PMID 34660575, 2021).
breast carcinoma (1 paper, 2021). "However, MRGBP was less expressed in some tumors such as brain and central nervous system cancer, breast cancer, leukemia, and other cancer." (PMID 34660575, 2021).
gastric cancer (1 paper, 2022). A primary or metastatic malignant neoplasm involving the stomach. "The results showed that high expression of MRGBP was associated with advanced head and neck squamous cell carcinoma, suggesting that MRGBP may be a marker for early or advanced gastric cancer." (PMID 35924262, 2022).
glioma (1 paper, 2021). A benign or malignant brain and spinal cord tumor that arises from glial cells (astrocytes, oligodendrocytes, ependymal cells). "Moreover, we investigated the prognostic value of MRGBP in LGG using the Chinese Glioma Genome Altas (CGGA) and GEO dataset (GSE 4412)." (PMID 34660575, 2021). "Furthermore, we explored MRGBP expression and the relationship between MRGBP expression and macrophage infiltration using immunohistochemical analysis in lower grade glioma (LGG)." (PMID 34660575, 2021).
head and neck squamous cell carcinoma (1 paper, 2022). A squamous cell carcinoma that arises from any of the following anatomic sites: lip and oral cavity, nasal cavity, paranasal sinuses, pharynx, larynx, and salivary glands. "In conclusion, MRGBP can serve as an independent prognostic biomarker related to immune invasion of head and neck squamous cell carcinoma." (PMID 35924262, 2022). "In head and neck squamous cell carcinoma, increased expression of MRGBP may be an independent prognostic biomarker and is related to the immune invasion." (PMID 35924262, 2022). "However, the role and clinicopathological significance of MRGBP in head and neck squamous cell carcinoma (HNSC) are unclear." (PMID 35924262, 2022).
liver cancer (1 paper, 2022). An epithelial or non-epithelial malignant neoplasm that arises from the liver. "MRGBP may be a new biomarker to predict the prognosis of liver cancer and a therapeutic target related to immune infiltration." (PMID 35924262, 2022).
lymph node metastasis (1 paper, 2017). "Furthermore, our research suggested that increased MRGBP expression in PDAC tissues was strongly associated with high TNM stage and poor prognosis, but not with lymph node metastasis, distant metastasis, vascular invasion." (PMID 28969065, 2017).
ovarian carcinoma (1 paper, 2021). A malignant neoplasm originating from the surface ovarian epithelium. "MRGBP was negatively associated with invasion (cor = −0.433, P < 0.001) in ovarian cancer." (PMID 34660575, 2021).
primary immunodeficiency (1 paper, 2021). "The ribosome, cell cycle, DNA replication, homologous recombination, primary immunodeficiency, Fc gamma R-mediated phagocytosis, type I diabetes mellitus, spliceosome, and leishmania infection pathways were differentially enriched in the MRGBP high-expression group." (PMID 33761715, 2021).
cancer (12 papers, 2010 to 2023). A tumor composed of atypical neoplastic, often pleomorphic cells that invade other tissues. "Among MRGBP coding chain mutations, C > T and G > A types were the most common, and other types of mutations were rarely found in different cancers." (PMID 34660575, 2021). "In most cancers, MRGBP expression was associated with tumor stage and was significantly higher in patients with advanced stages." (PMID 34660575, 2021). "We further verified whether the expression of MRGBP was associated with MSI in various cancers." (PMID 34660575, 2021). "In this study, we used the TCGA database to study the expression profile of MRGBP in various cancers." (PMID 35924262, 2022). "This study comprehensively analyzed the expression of MRGBP in the cancer database and its relationship with the prognosis of HNSC patients." (PMID 35924262, 2022). "Many studies have discussed the relationship between the expression level of MRGBP and the prognosis of various malignant tumours." (PMID 35924262, 2022). "This study comprehensively analyzed the expression of MRGBP in the cancer database and its relationship with the prognosis of cancer patients." (PMID 35924262, 2022). "LGG and LIHC was selected as representative cancer types for further study, the results of immunohistochemistry indicated that the protein levels of MRGBP were significantly elevated in tumor tissues." (PMID 34660575, 2021). "Subsequently, we analyzed the correlation between the level of MRGBP expression and prognostic value in pan-cancer by using TCGA databases." (PMID 34660575, 2021). "In this research, the expression profile, prognostic value of MRGBP, and the relationship between MRGBP and immune infiltration were explored in 33 types of cancer." (PMID 34660575, 2021). "To better understand the potential mechanisms of MRGBP in cancer, we estimated the functional status of MRGBP in the CancerSEA database." (PMID 34660575, 2021). "Subsequently, the correlation between MRGBP expression levels and the levels of 21 immune cell infiltrates in human cancers was studied." (PMID 34660575, 2021). "Our results revealed that MRGBP was highly expressed in most cancer tissues compared with normal tissues." (PMID 34660575, 2021). "In this report, we performed a multifaceted analysis of MRGBP in human cancers including its expression levels in tumors, normal tissues, and cell lines, the relationship between MRGBP expression and patient prognosis, TMB, and MSI." (PMID 34660575, 2021). "Several studies have shown that MRGBP expression was increased in most cancer cell lines such as PDAC cell lines and the proliferative, migratory and invasive capacities of ASPC-1 and Mia PaCa-2 were significantly reduced." (PMID 34660575, 2021). "The differences in MRGBP expression in tumor and normal tissues were explored using data from The Cancer Genome Atlas, Gene Expression Omnibus and ONCOMINE." (PMID 34660575, 2021). "MORF4-related gene-binding protein (MRGBP), which is also known as chromosome 20 open reading frame 20 (C20orf20), is commonly highly expressed in several types of malignant tumors and tumor progression." (PMID 28969065, 2017). "Scholars suggested that MRGBP has an important function in proliferation of cancer cells through the regulation of bromodomain containing 8 (BRD8)." (PMID 28969065, 2017). "To investigate a possible function of elevated MRGBP expression in the proliferation of cancer cells, we prepared plasmids that express MRGBP- and EGFP-specific shRNAs with neomycin resistant gene (psiH1BX-MRGBP1, -MRGBP2, -MRGBP3, and -EGFP)." (PMID 20051959, 2010). "Interaction of MRGBP with BRD8 is probably a key for determination of MRGBP function in cancer cells." (PMID 20051959, 2010). "To disclose the mechanism(s) underlying the decrease of viable cells by MRGBP knockdown, we investigated induction of apoptosis, cell cycle progression, and DNA synthesis in cancer cells treated with MRGBP siRNA." (PMID 20051959, 2010).